MSLN (mesothelin)
Diseases named in the same sentence as MSLN in open-access papers (continued):
Sharing a sentence is not in itself a finding about the gene and the disease.
tumor (continued). "The proteolytic processing that occurs when the MUC16 is shed from the surface of the tumor cells or subsequent digestion of the N-linked glycans by glycosidases in the peritoneal fluid may alter the soluble MUC16 and make it a less effective ligand for mesothelin." (PMID 17067392, 2006). "Furthermore, it demonstrated selectivetargeting across MSLN-expressing xenografts (A431-G9, A431-H9, HCT116,and AsPC-1), consistently yielding a strong tumor signal even in HCT116tumors with low-to-moderate MSLN expression by IHC and WB." (PMID 41439681, 2026). "MSLN has restricted expression in normal tissues but is abnormally overexpressed in a variety of solid tumors including TNBC, and potentially play roles in tumor cell proliferation, survival." (PMID 41513618, 2026). "Overall, this study demonstrates that targeting MSLN can improve neoantigen vaccine induced immune efficacy by reducing apCAFs to interrupt the conversion of naive CD4+ T cells to Tregs, and therefore increase the infiltration of tumor‐specific T cells." (PMID 39887656, 2025). "Therefore, the development of therapeutic strategies targeting the interactions between MSLN and MUC16, along with the exploration of their combined application with existing therapies, is anticipated to yield new breakthroughs in tumor therapy." (PMID 41400642, 2025). "Interestingly, in vitro silencing of MSLN resulted in a transition from the immune-suppressive TME (Tregs and CD206 + TAM) to the tumor suppressive one (CD8 + T-cells and CD86 + TAM), suggesting the MSLN functional involvement in this process." (PMID 41335396, 2025). "Additionally, Cherkassky previously demonstrated the synergistic effects of combining anti-MSLN-CAR-T cells with anti-PD-1 antibody, leading to enhanced CAR-T cell anti-tumor ability, which holds promise for extending patient survival." (PMID 41450878, 2025). "Also, histoepigenetic analysis classified tumor samples based on intrinsic MSLN expression, revealing discrete subgroups in PDAC and MPM, further supporting the role of epigenetic regulation in mesothelin expression." (PMID 40227616, 2025). "An interesting feature of the mesothelin/CD3 2 + 1 bispecific is that it can increase retention of target antigen on the surface of the cell by controlling endosomal trafficking and, thus, enable T cell engagement and killing of tumor cells." (PMID 40507272, 2025). "Interestingly, these anti-mesothelin CAR γδ T cells perform even better when IL-15 expression is increased, leading to profound anti-tumor effects both in vitro and in vivo." (PMID 40148988, 2025). "Mesothelin, through its interaction with MUC16, contributes to metastatic progression and immune suppression; CAR-T-cells targeting mesothelin have demonstrated potential in reducing tumor burden." (PMID 40940908, 2025). "Here, a nanobody-based, mouse mesothelin-targeting CAR-T cell (A101) was developed, achieving effective primary tumor suppression, metastasis reduction, and improved survival after a single dose in immunocompetent, syngeneic mouse models without lymphodepletion." (PMID 40568084, 2025). "Although only a limited number of clinical trials have evaluated CAR-NK products based on NK92, PB-NK, and UCB-NK cells, there is growing interest in targeting common tumor antigens like Roundabout homolog 1 (ROBO1), NK cell-activating receptor (NKG2D), MSLN, HER2, and MUC1." (PMID 40299429, 2025). "Additionally, the mesothelin-targeted CAR with the HPA-bridge resulted in improved overall survival and induced either similar or greater tumor control compared to the HPA-CAR, depending on the donor." (PMID 41372740, 2025). "This made it an ideal system to test the contribution of the glyco-bridge, since CAR-T cells targeting mesothelin would not engage the tumor cells directly." (PMID 41372740, 2025). "The interaction between MSLN and MUC16 (CA125) plays a significant role in tumor progression." (PMID 41400642, 2025).
tumor (continued). "In contrast to hematologic malignancies, where lineage-specific markers such as CD19 and BCMA offer consistent targeting, many solid tumor-associated antigens (e.g., mesothelin, B7-H3, GPC3) are variably expressed and are not uniformly tumor-specific." (PMID 40723278, 2025). "These include dual-target CARs that require recognition of two tumor-associated antigens (e.g., B7-H3 and GPC3, or EGFRvIII and mesothelin) or use AND-/NOT-gating logic to fine-tune activation thresholds." (PMID 40723278, 2025). "Also, MSLN has been demonstrated to influence OCT-2 and NF-κB, resulting in the reduced expression of the tumor suppressor miR-198." (PMID 40227616, 2025). "MSLN expression has been shown to heighten tumor aggressiveness, albeit this impact is not exclusively attributable to its interaction with MUC16." (PMID 40227616, 2025). "Both MSLN and CA-125 are being explored as therapeutic targets, with approaches including monoclonal antibodies, antibody-drug conjugates and CAR-T cell therapies to disrupt their interaction and inhibit tumor growth." (PMID 40227616, 2025). "In the H9 tumor model, PBMC, NKT and γδT significantly inhibited the tumor growth in the presence of the MSLN/CD3 bsAb, However, the body weight of the NKT-treated mice decreased the most, followed by the PBMC-treated mice, while the γδT-treated mice maintained stable body weight." (PMID 39995672, 2025). "By contrast, targets such as MSLN and CEA, despite their overexpression in CRC, face notable challenges that may limit their clinical utility, primarily because of concerns about off-tumor effects." (PMID 39805063, 2025). "Single-cell analysis revealed that MSLN was predominantly expressed in tumor cells, with minimal expression in non-tumor cells (e.g., stromal or immune cells) within the tumor microenvironment." (PMID 40792273, 2025). "Consistently across two tumor models, the NKG2D/CD28&MSLN CAR-T group exhibited a higher CAR-T cell count per microliter of blood at both time points, with a greater proportion of naïve T cells and lower PD-1 expression compared to the traditional CAR-T group." (PMID 40181405, 2025). "Preclinically, the STING agonist cGAMP both directly activates NK cells and sensitizes PDAC cells (e.g., ULBP2/5/6 upregulation and apoptosis), and, in combination with mesothelin-targeted CAR-NK-92, achieves superior tumor control and prolongs survival in mouse models." (PMID 40940881, 2025). "MSLN significantly enhanced the BM abilities of NSCLC cells by facilitating the expression and activation of MET through the c-Jun N-terminal kinase signaling pathway, which allowed tumor cells to disrupt tight junctions and the integrity of the BBB." (PMID 39998776, 2025). "We treated brain endothelial cells with conditioned medium from brain metastatic cells and found that knockdown of MSLN inhibited the degradation of VE-cadherin, JAM-A and claudin-5 on brain endothelial cells, significantly reducing the number of tumor cells migrating across the endothelial layer." (PMID 38570866, 2024). "As CAR-T cells are currently under investigation though MSLN and PD-1 are both kinds of consistent cell-surface proteins at a relatively low level in normal tissues, they are not tumor-specific antigens." (PMID 38203736, 2024). "Interestingly, the most potent anti-tumor effect was seen when animals were pretreated with FRβ CAR-T cells, followed by tumor-directed anti-mesothelin CAR-T cells." (PMID 38727262, 2024). "Tumor cells with different HLA typing can be artificially modified with relative HLA‐restricted peptides and be recognized by specific TCR‐T cells, since there are several TCR‐T products (such as MAGE‐A4 TCR‐T and MSLN TCR‐T) that have entered clinical trial." (PMID 38974711, 2024).
tumor (continued). "They showed that anti-mesothelin CARs facilitate the delivery of PTX and cytotoxic granules inside nanovesicles to tumor cells, and the anti-PD-L1 CARs on the surface of LipCExo@PTX efficiently reverse the immunosuppressive effect of the tumor microenvironment." (PMID 39490997, 2024). "Consistent with the immunofluorescence observations, we found that conditioned medium from tumor cells with MSLN knockdown did not induce as much degradation of the cadherin, JAM-A and claudin-5 expression patterns among hBMVEC monolayers." (PMID 38570866, 2024). "Compared with conventional anti-MSLN CAR-T cells, CAR-T cells coexpressing CCR2b exhibited increased CCL2-induced calcium flux and transport, increased levels of IL-2, IFN-γ, and TNF-α, and enhanced cytotoxicity against MSLN+ tumor cells in vitro." (PMID 39023820, 2024). "Next, to assess whether CAR-T cell therapy after LDRT was also effective in a different tumor model, we implemented a similar therapeutic approach in NSG mice implanted with the mesothelin-positive human CAPAN-2 cell line." (PMID 39445067, 2024). "In addition, more ADGRE1 RNA molecules were detected in IMSA101-treated tumors, while RNA-count of the tumor antigens, mouse mesothelin or human CD19, was lower in these cohorts consistent with anti-tumor response." (PMID 38730243, 2024). "The silencing of MSLN leads to decreased expression of β-catenin, which is an important marker of epithelial–mesenchymal transition (EMT); this effect is likely to affect the invasion of tumor cells." (PMID 39023820, 2024). "Moreover, we analyzed MSLN IHC protein expression in CRC normal paired/matched and CRC tumor tissues." (PMID 39174744, 2024). "In vivo experiments showed that both ATTO 647N and [68Ga]Ga-NODAGA-S1 rapidly and specifically accumulated in mesothelin positive tumours compared to mesothelin negative tumours or irrelevant Nb with a high tumour/background ratio." (PMID 37388728, 2023). "In addition, we examined the anti-MSLN CAR-T and MT CAR-T cell phenotype after co-culture with tumor cells." (PMID 37359558, 2023). "Secondly, there is a risk of antigen‐escape, which is the selective survival of antigen‐negative tumour, if only a minority of cases have MSLN expression in ≥ 50% of tumour cells." (PMID 37040900, 2023). "T cells were detectable in all primary tumor/ovarian tissues isolated from sacrificed mice, regardless of MSLN-CAR treatment group." (PMID 36746513, 2023). "Tumor-specific antigens have also been targeted in several clinical trials reducing off-tumor toxicities—for instance, NCT04489862 is an early phase I study which aims to target α-PD-1 and MSLN in non-small cell lung cancer at Wuhan Union Hospital, China." (PMID 37520522, 2023). "A poor OS was associated with non-operated patients [HR, 3.42 (1.15–10.16)] with low tumor MSLN expression [HR, 2.58 (1.09–6.10)], high levels of PD-L1, and low infiltration of T cells CD4+ in the TME [HR, 3.81 (1.58–9.18)]." (PMID 37901248, 2023). "The same mesothelin-targeted engineered T cell receptor is used in TC-510, but it is also engineered with a PD-1/CD28 switch so that PDL-1 expression on the tumor (either baseline or induced by inflammatory cytokines) results in increased activity of the engineered cells rather than inhibition." (PMID 37296902, 2023). "In the phase I study of CRS-207 monotherapy, no objective tumor response was seen, but there was evidence of activation of mesothelin-specific T cells." (PMID 37296902, 2023). "We found that the risk of death was three-fold higher among non-operated patients with low tumor cell MSLN expression, high PD-L1 levels, and low infiltration of T cells CD4+ in the TME." (PMID 37901248, 2023). "Mesothelin (MSLN) is a differentiation antigen present on mesothelial cells that is overexpressed in various cancers, including ductal pancreatic, ovarian, and lung tumors, and has been used as a tumor biomarker and target for treatment." (PMID 37835395, 2023).
tumor (continued). "To validate the tumor killing effect of CAR-T cells, we first designed and generated anti-MLSN CAR-T cells with a highly efficient second-generation human-derived scFv targeting MSLN, which was screened from a human-derived scFv phage display library." (PMID 37359558, 2023). "In the context of HGSC, Banville and colleagues conducted an investigation to identify antigens that could be targeted via combinatorial CAR-T platforms by investigating the simultaneous expression of FRα, mesothelin, and CA125 in different HGSC tumor samples." (PMID 38146364, 2023). "Furthermore, while previously resistant, pre-treatment with FAP UCAR T-cells now sensitized these tumors to Mesothelin (Meso) UCAR T-cell infiltration and anti-tumor cytotoxicity." (PMID 37251405, 2023). "Fusing a non-pathogenic, structurally modified version of the Sda1, SLO, or Scl1 to a TAA like mesothelin, a prominent TAA in PDAC could be beneficial in inducing anti-tumor responses." (PMID 37588093, 2023). "Mechanistically, the elimination of a mesothelin-negative tumor cell was traced back to bystander effects emanating from endogenous CD8+ T cells." (PMID 36768665, 2023). "Overall, TORC1 and MSLN may be candidate markers predicting the progression from HGIL to ISL28, 31, 32 and STUB1 was reported to act as a tumor suppressor." (PMID 35920319, 2023). "Moreover, tumor clusters had higher expression levels of tumor makers, including LAMC2, MSLN, TFF2, and CEACAM5, compared with ductal clusters, which further verified their tumor identity." (PMID 36944944, 2023). "PD-L1+, FAS+ and CD73+ tumor cells were found at higher frequencies within MSLN+ SKOV-3 cells compared with MSLN- SKOV-3 cells, regardless of treatment group M28z and MBBz." (PMID 36746513, 2023). "A listeria monocytogenes vaccine expressing mesothelin (CRS-207) showed a good safety profile, induced positive changes in the tumor microenvironment (TME), and achieved objective tumor responses in 89% of the treated MESO patients with a median 14.7-month OS when combined with cyclophosphamide." (PMID 35893817, 2022). "In a phase I study, the anti-MSLN antibody MMOT0530A radiolabeled with 89Zr- demonstrated maximum tumor uptake four days’ post-injection (mean SUVmax of 13.1 (±7.5)), with uptake observed in at least one tumor lesion in all patients (range 1–8)." (PMID 35326605, 2022). "Compared to the purple line, representative of a MSLN CAR-T that does not distinguish tumor from normal cells, the blue line has a span of activation that is less than half the magnitude, even at the maximum MSLN level of >1,000,000 copies/cell." (PMID 35359952, 2022). "We previously showed that MSLN-specific T cell receptor (TCR)-engineered T cells preferentially accumulate within established tumors, delay tumor growth, and significantly prolong survival in the ID8VEGF mouse model that replicates many aspects of human disease." (PMID 35264436, 2022). "Ovarian cancer has been treated by CAR-NK targeting mesothelin antigens or CD24 receptors, while pancreatic cancer has been targeted by CAR-NK cells via recognition of ROBO1 antigens or folate receptors, used as an antigen for therapy of both tumor types." (PMID 36612114, 2022). "Anetumab ravtansine is an antibody–drug conjugate (ADC) comprised of a humanized anti-mesothelin antibody conjugated to DM4 (a maytansinoid tubulin inhibitor), which showed potent killing of tumor cells expressing mesothelin." (PMID 35326701, 2022). "Furthermore, as OVCAR8 and OVCAR3 cells express mesothelin (MSLN) and MSLN-targeted CAR-T (MCAR-T) cells are being actively tested in clinical and preclinical studies, we also studied the treatment of tumor-bearing mice with MCAR-T cells." (PMID 35406547, 2022). "Further antigens were considered, including MSLN, since it is expressed in 69% of lung adenocarcinoma (1/5 patients) and not in normal lung tissues and reduced tumor burden in mouse models." (PMID 35814023, 2022).
tumor (continued). "Three hub genes, COL7A1, MSLN, and CHRDL1, were identified from 513 robust DEGs using a series of bioinformatics methods, which were significantly correlated with tumor-infiltrating monocytes as well as effective indicators of prognostic outcomes for LUSC patients." (PMID 35993054, 2022). "Indeed, pre-clinical studies have shown anti-tumor activity of TTCs as monotherapy across a broad range of tumor types, and TTCs targeting HER2, PSMA, MSLN, and CD22 are under investigation in clinical studies." (PMID 36726355, 2022). "Moreover, in a humanized murine model of OC designed to express human mesothelin, mesothelin-targeted IVT CAR T-cells effectively reduced tumor growth." (PMID 36153626, 2022). "Mesothelin-targeted thorium conjugate has been investigated in MSLN-positive ovarian cancer models, with significant anti-tumor activity seen when MSLN-TTC was used in single-dose regimens in cell line-derived xenografts and single- and multiple-dose regimens in patient-derived xenografts." (PMID 36726355, 2022). "Firstly, MSLN has been shown to be a specific and safe target in MM; and secondly, the ongoing research on CAR design and efficacy enhancement of anti- MSLN CAR T cells as well as their combination with CI and oncolytic viruses has increased tumor infiltration, efficacy and persistence." (PMID 33588928, 2021). "For the expression of antigens in tumor tissues, the results indicated that the percentage of FOLR1+MSLN+ cancer cells was significantly decreased in the Tandem-CAR T cell group, while single-target CAR T cells only reduced the corresponding antigen level (p <0.0001)." (PMID 34803504, 2021). "It was hypothesized that once bound to mesothelin-overexpressing tumor cells, furin-mediated cleavage would release CXCL16 from the NRPbody and thereby recruit NK cells to the tumor sites." (PMID 33407739, 2021). "In order to better characterize these two cell populations, an additional FACs panel including a tumor marker (EpCAM), stem cell markers (CD44, CD24, and CD133) and mesenchymal‐like and mesothelial cell markers (CD90, podoplanin and mesothelin) was established." (PMID 34060699, 2021). "In this regard, the administration of anti-mesothelin CAR T-cells in six patients with recurrent OC stimulated an immune response with a clearance of pleural effusion demonstrated in one participant, suggesting a direct anti-tumour effect." (PMID 34944851, 2021). "The results so far are encouraging as all trials show manageable toxicity (mostly lower grade adverse effects and no ‘on target/off tumor’ toxicities), thereby confirming MSLN as a promising target for CAR T cell therapy against MM." (PMID 33588928, 2021). "Anti-MSLN CAR T cells in this trial also carry a suicide switch based on the iCasp9 cell-suicide system, which can be activated in case of severe ‘on target/off tumor’ toxicities." (PMID 33588928, 2021). "Recently, a soluble form of mature MSLN (soluble mesothelin-related protein, SMRP) derived by alternative splicing or protease cleavage, was also reported, and it is currently assessed as a tumor biomarker." (PMID 33418877, 2021). "While tumor-naïve MSLN knockout mice do not present with an abnormal phenotype, the contribution of host MSLN expression to peritoneal tumor dissemination has not been explored." (PMID 34830322, 2021). "To correlate the specificity of viral entry into host cells to cellular toxicity, we searched for a cell line not expressing human MSLN, in which to obtain stable expression of the tumor antigen." (PMID 33418877, 2021). "Tumor cells in the presence of mesothelial cells, regardless of MSLN expression, facilitated MCA formation demonstrated by tightly packed spheroids." (PMID 34830322, 2021). "In fact, mesothelin-specific CD8+ T cell responses were observed earlier with Cy/GVAX+CRS-207 than Cy/GVAX only suggesting that the expected synergy of the prime boost approach was realized in terms of both efficacy and anti-tumor immune response." (PMID 33936058, 2021).